KRT17 (keratin 17)
Diseases named in the same sentence as KRT17 in open-access papers (continued):
Sharing a sentence is not in itself a finding about the gene and the disease.
triple-negative breast carcinoma (7 papers, 2018 to 2026). An invasive breast carcinoma which is negative for expression of estrogen receptor (ER), progesterone receptor (PR), and human epidermal growth factor receptor 2 (HER2). "The study showed that KRT17 was highly expressed in triple-negative breast cancer cells and that the high expression of KRT17 was associated with reduced 5-years disease-free survival in patients with advanced cancer." (PMID 35281081, 2022). "The positive expression rate of KRT17 was 82% (28/34) in the triple-negative breast cancer cells, The positive expression rate of KRT17 was 46% (52/112) in non-triple-negative breast cancer cells and 0 (0/15) in lobular carcinoma." (PMID 35281081, 2022). "On the other hand, the C19MChigh group harbored significantly upregulated expression of KRT5, KRT14 and KRT17 mRNAs compared to C19MClow group, the candidate “positive markers” of basal-like triple negative breast cancers (TNBCs)." (PMID 30335837, 2018). "The positive expression rate of KRT17 in non-triple-negative breast cancer was 46% (52/112)." (PMID 35646078, 2022). "Triple negative breast cancers (TNBCs) are known to express low PGR, ESR1, and ERBB2, and high KRT5, KRT14, and KRT17." (PMID 30335837, 2018). "The expression rate of KRT17 in triple-negative breast cancer exceeds 80%, whereas the expression rate in non-TNBC is less than 50%, and its expression is positively correlated with poor breast cancer prognosis." (PMID 37634232, 2023). "KRT17 and GFRA3 were negatively correlated with LCK in triple-negative breast cancer, while they were positively correlated in other classifications, with the exception of KRT17, which was negatively correlated with LCK in normal-like tissues with the highest correlation level." (PMID 37686072, 2023).
basal cell carcinoma (6 papers, 2020 to 2024). A carcinoma involving the basal cells. "In basal cell carcinoma, the genetic ablation of keratin 17 decreased inflammation and polarized the inflammatory response towards T-helper-2-cells." (PMID 37046726, 2023).
COVID-19 (6 papers, 2020 to 2025). A disease caused by infection with severe acute respiratory syndrome coronavirus 2. "The SOX2−/TP63+ Wnt-activated transcriptional signature of KRT5−/KRT17+ basaloid cells in IPF and SOX2− signature of KRT5−/KRT17+ basaloid cells in post-COVID-19 fibrosis suggest that loss of SOX2 expression may explain the formation of these distinct dysplastic lesions in lung disease." (PMID 38182591, 2024). "However, according to scRNA-seq data, PLAU expression increased only in certain cell types (KRT17+ KRT5-) in COVID-19 patients; uPA protein accumulation may be linked to abnormal internalization and lysosomal degradation, directed by uPAR." (PMID 36674896, 2023). "These KRT5−/KRT17+ cells from COVID-19 patients were found to express SOX2 at a lower level than other cell types." (PMID 38182591, 2024). "In human IPF and COVID-19 damaged lungs, loss of SOX2 correlates with the appearance of aberrant KRT5−/KRT17+ epithelial cells." (PMID 38182591, 2024). "Our data show that IPF and post-COVID-19 are similar in that they both exhibit KRT5−/KRT17+/SOX2− cells." (PMID 38182591, 2024). "PLAU and PLAUR expression was also observed in a fraction of cells from a pro-fibrogenic KRT17+ KRT5- population in COVID-19 and PF patients, though the overall number of PLAU+ and PLAUR+ cells in this population was still low (median normalized expression 0)." (PMID 36674896, 2023). "We observed flat KRT17-positive cells resembling alveolar type 1 cells in the distal lung of the patient with early COVID-19 disease who died (palliative COVID-19)." (PMID 33257409, 2020).
cyst (6 papers, 2020 to 2024). A sac-like closed membranous structure that may be empty or contain fluid or amorphous material. "It has been speculated that the distribution of KRT17 in pilosebaceous glands and glandular structures may be responsible for cyst formation in PC-2." (PMID 39606016, 2024). "We validated the clustering outcomes by using specific antibodies for different nephron segments, including LRP2, SLC12A1, CDH16, KRT17 and two classical markers CD10 and AQP2(the marker of PT and CD, respectively) for IHC staining of cyst epithelial cells." (PMID 34815804, 2021). "We studied the cell origin of cyst epithelial cells by conducting differential gene expression analysis and established genetic markers (LRP2, SLC12A1, CDH16, and KRT17) 21, 22 of renal tubules and CD in the epithelial cell populations, respectively." (PMID 34815804, 2021). "In contrast, explanted lung tissue from cases 1 and 2 who underwent lung transplantation contained KRT17-positive cells that were localized near COL1A1-positive cells and in some regions appeared to line the cyst-like structures revealed by standard histology." (PMID 33257409, 2020).
diabetes (6 papers, 2023 to 2025). "It has been reported that increased plasma levels of APEX1, CD55, PSME2, and SERPINC1 are significantly associated with hypertension, and increased plasma levels of APEX1, CD55, GGCT, KRT17, PSME2, and SERPINC1 are associated with diabetes." (PMID 41156831, 2025). "Increased KRT17 protein expression was observed in skin of patients with diabetes by Western blotting and immunohistochemistry tests." (PMID 38205163, 2024). "To further elucidate the relationship between KRT17 and diabetes status, we investigated the expression of KRT17 in the skin tissue of diabetic mice." (PMID 38205163, 2024). "The expression and arrangement patterns of cytokeratin 17 in our results predict the pathological effect of both diabetes mellitus and duct ligation on the intracellular filament system of the salivary gland parenchyma in a different way that interferes with saliva production leading to dry mouth." (PMID 35728611, 2023). "We hypothesize that KRT17, which is upregulated under diabetic pathological conditions, could play a regulatory role in diabetic skin lesions through its effects on HaCaT cell proliferation and migration." (PMID 37929023, 2023). "Furthermore, we tested the expression of KRT17 in the skin of patients with diabetes." (PMID 38205163, 2024). "Relative expression of KRT17 and COL1A1 was both higher in ESCC patients with diabetes and correlated with blood glucose levels." (PMID 38979664, 2024). "The chi‐square test and correlation analysis demonstrated that the relative expression levels of keratin 17 (KRT17) and collagen type I α1 chain (COL1A1) were significantly higher in EC with diabetes." (PMID 38979664, 2024).
esophageal squamous cell carcinoma (6 papers, 2008 to 2023). Esophageal squamous cell carcinoma (ESCC) is a type of esophageal carcinoma (EC) that can affect any part of the esophagus, but is usually located in the upper or middle third. "In addition KRT17 has been found up-regulated in human esophageal squamous cell carcinoma (ESCC) and associated to invasiveness." (PMID 18302799, 2008). "In esophageal squamous cell carcinoma the upregulation of protein KRT17 was found to be detrimental to survival." (PMID 36010616, 2022). "The expression of KRT17 has been found to be up-regulated in cancerous tissues in cervical, tongue, oral, and esophageal squamous cell carcinomas." (PMID 22140553, 2011). "KRT17 triggers the AKT-mediated signaling pathway and induces EMT, while it is strongly correlated with malignant transformation and worse prognosis in esophageal squamous cell carcinoma (ESCC) patients." (PMID 36949761, 2023).
Palmoplantar keratoderma (6 papers, 2018 to 2023). Abnormal thickening of the skin of the palms of the hands and the soles of the feet. "Mutations in Krt17 and Krt16 are associated with Palmoplantar Keratoderma (PPK) lesions (i.e. abnormal thickening of palm skins) in humans, and mice that lack the Krt16 gene develop spontaneous lesions resembling human PPK." (PMID 31968015, 2020). "However, the disease-causing variants observed in type I keratins (KRT9, KRT10, KRT13, KRT14, KRT16, KRT17) occur mostly in the rod domains (1A, 1B and 2B), except in the case of palmoplantar keratoderma." (PMID 34991727, 2022).
pancreatic ductal adenocarcinoma (6 papers, 2019 to 2025). An infiltrating adenocarcinoma that arises from the epithelial cells of the pancreas. "Moreover, the role of KRT17 as a prognostic and predictive biomarker in pancreatic ductal adenocarcinoma (PDAC) sheds significant light on its potential utility in clinical settings." (PMID 40563550, 2025).
alopecia (5 papers, 2012 to 2024). Hair loss usually from the scalp. "The effects of loss of KRT17 on hair development and fineness are similar to the symptoms of hormone-sensitive hair loss." (PMID 39336745, 2024). "Physiologically, K17 plays a key role in maintaining normal hair follicle functions; accordingly, mice deficient for Krt17 exhibit severe alopecia after birth resulting from TNF receptor-mediated apoptosis." (PMID 35096815, 2021). "However, given the observed alopecia, it is somewhat surprising that transcripts for hair-follicle-specific keratins (Krt6a, Krt6b, and Krt17) were increased." (PMID 34445339, 2021).
dermatitis (5 papers, 2009 to 2025). An inflammatory process affecting the skin. "The expression of keratin 17 is induced by ionizing radiation (IR), and high levels of keratin 17 are characteristic of IR-induced dermatitis." (PMID 39194725, 2024). "Since abnormal expression of KRT6B and KRT17 may affect their structural role in the epidermis, these proteins might represent a biomarker for skin disorders." (PMID 30061793, 2018).
Hyperkeratosis (5 papers, 2020 to 2023). Hyperkeratosis is a histopathological term defining a thickened stratum corneum and may be present in many different skin conditions, with many possible overlaps. "The genetic mutation in KRT17 is related to PC, which mainly manifests itself as hyperkeratosis of the nails, palm, and pelma." (PMID 33763026, 2021). "We speculate that KRT17 is upregulated under high glucose and promotes keratinocyte proliferation and migration caused hyperkeratosis, through the c-MYB/PI3K-AKT pathway, contributing to delayed wound healing." (PMID 37929023, 2023). "The overlapping DEGs included genes associated with hyperkeratosis (upregulated LCE3E and TMEM45A), wound healing (upregulated KRT17, IL36G, TNC, and TGFBI), barrier defects (downregulated FRAS1 and BCL11A), and response to infection (upregulated IL36G, ADAP2, DFNA5, RFTN1, LITAF, and TMEM173)." (PMID 34506598, 2021).
lung adenocarcinoma (5 papers, 2019 to 2024). A carcinoma that arises from the lung and is characterized by the presence of malignant glandular epithelial cells. "Studies in other groups have also shown that the RNA and protein levels of KRT17 are highly expressed in lung adenocarcinoma tissues and that the high expression of KRT17 is associated with advanced TNM stage and overall survival." (PMID 35281081, 2022). "The high expression of KRT17 suggests a poor prognosis in non-small cell lung cancer, especially lung adenocarcinoma." (PMID 35281081, 2022). "KRT17 can enhance the proliferation, migration, and invasion capacities of lung adenocarcinoma cells, thereby promoting tumor progression." (PMID 31466283, 2019). "However, the over-expression of KRT17 can promote the proliferation and invasion of lung adenocarcinoma cells." (PMID 35281081, 2022). "Similarly, KRT17 is highly expressed in lung adenocarcinoma cell lines, and KRT17 knockout can inhibit cell proliferation and invasion." (PMID 35281081, 2022). "The prognosis of patients with lung adenocarcinoma was significantly affected by six genes (KRT6A, VEGFC, KRT14, KRT17, SNORA12, and KRT81) related to FSTL3." (PMID 38240936, 2024). "Keratin 17 (KRT17), reported to promote lung adenocarcinoma via enhancing cell proliferation and invasion, showed a paradoxical anti-metastatic role of KRT17 both in vitro and in vivo in cancer xenografts in a single-cell lineage study." (PMID 35008645, 2021). "Concurrently, we will delve into the interactions between FSTL3 and other pertinent genes, such as KRT6A, VEGFC, KRT14, KRT17, SNORA12, and KRT81, to enhance our understanding of its role in lung adenocarcinoma progression and to pinpoint novel therapeutic targets." (PMID 38240936, 2024).
Nail dystrophy (5 papers, 2012 to 2025). Onychodystrophy (nail dystrophy) refers to nail changes apart from changes of the color (nail dyschromia) and involves partial or complete disruption of the various keratinous layers of the nail plate. "The KRT17 p.L99P mutation resulted in an increased number of involved fingernails and patients demonstrating 20-nail dystrophy." (PMID 39606016, 2024).
pancreatic adenocarcinoma (5 papers, 2022 to 2024). "Notably, high KRT17 signature expression predicted a worse survival in KRT17hi cancer type like pancreatic adenocarcinoma (TCGA_PAAD)." (PMID 38822440, 2024).
urothelial carcinoma (5 papers, 2021 to 2025). A malignant neoplasm derived from the transitional epithelium of the urinary tract (urinary bladder, ureter, urethra, or renal pelvis). "In urothelial carcinoma, KRT17 was shown to be co-expressed and co-localized with laminin receptor in highly tumorigenic cancer cell populations." (PMID 35706019, 2022). "In addition, keratin 17 is considered a novel cytologic biomarker for accurately distinguishing between recurrent urothelial carcinoma and benign urothelial cells." (PMID 36949761, 2023).
bladder urothelial carcinoma (4 papers, 2011 to 2023). "For the detection of non-bladder urothelial cancer (RPC and URC, N=32), KRT17 showed the best diagnostic performance with AUC 0.77 compared to 0.51 to 0.64 for urine cytology and BTA assays." (PMID 30214686, 2018). "We also observed hypomethylation of the KRT17 promoter in bladder urothelial carcinoma." (PMID 22140553, 2011).
breast invasive carcinoma (4 papers, 2022 to 2024). "In breast invasive carcinoma (BRCA) and kidney chromophobe (KICH), the expression of KRT17 was higher in normal tissues than in tumor tissues (p < 0.001)." (PMID 35646078, 2022).
diabetic foot ulcers (4 papers, 2021 to 2024). "The significant upregulation of KRT17 in chronic diabetic foot ulcer tissues suggests that KRT17 may be involved in the delayed healing of diabetic foot ulcers." (PMID 38205163, 2024).
Ewing sarcoma (4 papers, 2020 to 2023). A small round cell tumor that lacks morphologic, immunohistochemical, and electron microscopic evidence of neuroectodermal differentiation. "In Ewing’s sarcoma, KRT17 is the downstream expression gene of the glial-associated oncogene homologue 1 (GLI-1), which positively regulates KRT17 expression." (PMID 35281081, 2022). "The KRT17 gene has also been shown to be critical for proliferation of osteosarcoma, and for cellular adhesion and oncogenic transformation in Ewing’s sarcoma." (PMID 36009022, 2022). "Therefore, KRT17 mediated activation of Akt signaling is necessary for regulating cell adhesion in Ewing’s sarcoma." (PMID 35281081, 2022). "GLI-1 knockout significantly reduces Akt phosphorylation in Ewing’s sarcoma cells, and this effect can be salvaged by the overexpression of GLI-1 and KRT17." (PMID 35281081, 2022).
lymph node metastasis (4 papers, 2020 to 2025). "Further studies showed that positive KRT17 expression was associated with lymph node metastasis and higher pN staging." (PMID 35281081, 2022). "Multivariate analysis showed that pathological grade, lymph node metastasis, and up-regulated KRT17 expression was independent prognostic factors for overall survival." (PMID 35281081, 2022). "Analysis of the correlation between KRT17 and clinic-pathological features of LSCC patients uncovered that KRT17 expression was remarkably correlated with differentiation (P < 0.001), T classification (P < 0.01), lymph node metastasis (P < 0.05), and clinical stage (P < 0.05)." (PMID 36248412, 2022). "Moreover, the high expression of KRT17 has been found to be significantly correlated with clinicopathological parameters, including stage, invasion range and lymph node metastasis and is a predictor of poor prognosis in patients with advanced disease." (PMID 35281081, 2022). "In LSCC, we ascertained that expression of KRT17 in a panel of LSCC samples (42 cases) was positively correlated with the differentiation, T-typing, lymph node metastasis, and clinical stage." (PMID 36248412, 2022).
osteosarcoma (4 papers, 2022 to 2024). A usually aggressive malignant bone-forming mesenchymal neoplasm, predominantly affecting adolescents and young adults. "KRT17 knockout can inhibit proliferation, colony formation and glycolysis and can induce cell phase arrest of osteosarcoma cells." (PMID 35281081, 2022). "The results showed that KRT17 knockout inhibited the proliferation and glycolysis of osteosarcoma cells by inhibiting the Akt/mTOR/HIF1α pathway." (PMID 35281081, 2022). "KRT17 also activates the Akt/mTOR/hypoxia-inducible factor 1α (HIF1α) pathway by promoting proliferation and the Warburg effect, thereby promoting the growth of osteosarcoma cells." (PMID 35281081, 2022). "Knockdown of KRT17 may also decrease the viability and Warburg effect of osteosarcoma cells by significantly affecting the AKT/mTOR/hypoxia-inducible factor 1α (HIF1α) pathway and interrupting the expression of relevant genes." (PMID 36009022, 2022). "In osteosarcomas, KRT17 mRNA and protein expression levels are higher than in the adjacent normal bone tissue, but the expression level of KRT17 was not analysed and compared with clinicopathologic parameters in this study." (PMID 35281081, 2022). "The mRNA and protein expression levels of KRT17 in osteosarcoma cells were also higher than those in the normal bone hFOB cells." (PMID 35281081, 2022).
papilloma (4 papers, 2020 to 2024). A benign epithelial neoplasm that projects above the surrounding epithelial surface and consists of villous or arborescent outgrowths of fibrovascular stroma. "We found a novel regulator, stress keratin 17 (K17), was induced in expression following MmuPV1 infection, and that K17 was critical for preventing T cell infiltration in MmuPV1-induced papillomas by inhibiting the CXCL9/CXCL10/CXCR3 axis." (PMID 31968015, 2020). "Since stress keratin 17 has been implicated in regulating Th1/Th2 cytokine profiles in lesions arising in HPV16 transgenic mice, we tested whether a cellular immune response was necessary for papilloma regression in K17KO mice." (PMID 31968015, 2020).
renal cell carcinoma (4 papers, 2019 to 2023). "To obtain more insight into the biology of kidney cancers we have investigated KRT17 expression by immunohistochemistry in normal kidney, in papillary preneoplastic lesions and in 151 papillary and 692 conventional renal cell carcinomas placed on tissue microarray." (PMID 31602265, 2019). "We used the TCGA dataset of renal cell carcinoma patients and generated Kaplan-Meier analyses for the two most deregulated transcripts (CUBN and KRT17) as well as for the identified miRNA target genes." (PMID 31878355, 2019). "The neo-expression of KRT17 in conventional renal cell carcinomas, which derives from KRT17 negative proximal tubules showed a significant correlation with postoperative tumor relapse (RR=2.50; 95% CI=1.59-3.94; p<0.001)." (PMID 31602265, 2019).
viral infection (4 papers, 2021 to 2023). "KRT17 is not expressed in the epidermis of normal skin, but its expression can be induced under stress conditions, such as skin injury and virus infection." (PMID 35646078, 2022).
carcinoma in situ (3 papers, 2012 to 2021). "Representative samples including in situ carcinoma, keratinized cancer nests in well-differentiated cancer, small cancer nests in poorly differentiated cancer and a well-differentiated condylomatous tumor demonstrated ubiquitous expression of KRT17 in cancer." (PMID 27512993, 2016).